TNF (tumor necrosis factor)
Diseases named in the same sentence as TNF in open-access papers (continued):
Sharing a sentence is not in itself a finding about the gene and the disease.
depression (continued). "In patients with depression, the levels of CRP, IL-6, IL-12, and TNF-α are significantly elevated, indicating a pro-inflammatory state." (PMID 35087377, 2021). "Furthermore, a possible explanation could be that in the present study sample with a mean decrease of 24.1 points in MADRS score after ECT, the decline in depression severity is strong to an extent that only a relatively marginal reduction in the ratio TNF-α/BDNF is needed." (PMID 34841285, 2021). "UCMS induced anhedonia and hopeless behavior in mice, and changed expression levels of the depression-related genes BDNF, CREB, GR, SGK1, FKBP5, IL-1β, IL-6, and TNF-α in the frontal cortex and hippocampus." (PMID 34358084, 2021). "Expression of the microglial marker IBA-1 and inflammatory cytokines (IL1β, TNFα, BDNF) are up-regulated in the brain of patients with major depression and in animal models of depressive-like behavior." (PMID 34236532, 2021). "A significant association between the ratio of TNF-α/BDNF and depression severity was found: the higher the TNF-α/BDNF ratio, the greater the depression severity." (PMID 34841285, 2021). "Clinical studies have reported that the severity of depression in patients with PSD is positively correlated with the levels of IL-6, TNF-α, and IL-1β." (PMID 34725556, 2021). "In an animal experiment, significant depressive behavior was induced by injecting TNF-α or LPS into the lateral ventricle, Reichenberg found that TNF-α can induce depression and cognitive function changes in humans." (PMID 34479552, 2021). "More recent reviews resume that IL-1 ß, IL-6, TNF-α, and C-reactive protein (CRP) are the most consistently identified biomarkers of inflammation in depression." (PMID 34204400, 2021). "Increased plasma inflammatory markers including interleukin (IL)-6 and tumor necrosis factor (TNF)-α have been found in people with anxiety and depression particularly in those who fail to respond to classical treatments." (PMID 33807290, 2021). "Relatively consistent findings showed an increase in several cytokines, including interleukin-6 (IL-6), interleukin-1 (IL-1), tumor necrosis factor-alpha (TNF-α), and C-reactive protein (CRP) in patients with depressive disorder versus healthy controls (HCs)." (PMID 34576215, 2021). "Several studies have shown increased levels of TNF-α, IL-6, and C-reactive protein (CRP) in patients with depression." (PMID 33343332, 2020). "High levels of peripheral inflammatory cytokines and chemokines, including IL-1β, IL-6, IFN-γ, tumor necrosis factor-alpha (TNF-α), and CRP, have been reported in patients with depression." (PMID 32973758, 2020). "Patients with HD had significantly more depression (p < 0.05), higher scores on the CTQ assessment (p < 0.001), higher levels of plasma ACTH after the DST (p < 0.01) and TNF-alpha (p < 0.0001), but lower levels of plasma IL-6 (p < 0.001)." (PMID 31542994, 2020). "IL-1, IL-6, IL-1β, TNF-α, and CRP are considered markers of the initiation, relapse, and progression of depression." (PMID 32922295, 2020). "Clinical studies also show that pro-inflammatory cytokines, e.g. TNF-α, IL-1β, IL-6, CCL-2, and IL-18, increase in patients with depression or anxiety." (PMID 32010477, 2020). "In stress-induced animal models of depression, BDNF was shown to be markedly reduced by IL-1β and TNF-α and their downstream signaling pathways including NF-κB." (PMID 31019266, 2020). "Previous studies found that pro-inflammatory cytokines, including tumor necrosis factor-α (TNF-α) and interleukin (IL)-6, IL-1β, and C-reactive protein (CRP), are markedly increased in the blood and CSF of patients with depression." (PMID 32922295, 2020). "Our meta-analysis finds evidence that mean-scaled variability, measured as CVR, is reduced in patients with depression for CRP, IL-12 and sIL-2R, while it is unchanged for IL-3, IL-6, IL-18 and TNF α." (PMID 32113908, 2020).
depression (continued). "In our experiment, we found that TNF-α was increased in the PFC, hippocampus, amygdala, hypothalamus, and plasma in rats with depression-chronic pain comorbidity." (PMID 33144854, 2020). "High levels of neuro-inflammatory cytokines such as interleukin (IL)-1β, tumor necrosis factor-α (TNF-α), and IL-6 have been identified in patients with depression." (PMID 32922291, 2020). "Inflammatory cytokines, IL-6, TNF-α and IFN-γ are consistently upregulated in individuals with depression and many antidepressant medications have anti-inflammatory effects." (PMID 32539844, 2020). "A dysregulation in the levels of inflammatory proteins such as IL-12, TNF, IL-6 and IFN-γ have been found to be significantly correlated with depression." (PMID 32998701, 2020). "The proinflammatory cytokines tumor necrosis factor-α (TNF-α) and interleukin-6 (IL-6) play critical roles in the process of inflammation and can induce depressive disorders." (PMID 32184729, 2020). "Etanercept, a kind of tumor necrosis factor (TNF- α) antagonist, also has a strong antidepressant effect, which can improve depression symptoms and patient fatigue." (PMID 31231295, 2019). "We also found that positive changes in TNF-α, IL-6, IL-10 and CRP levels significantly correlated with higher reduction in depression symptoms." (PMID 31375659, 2019). "LPS activates the innate immune response, resulting in the secretion of various pro-inflammatory cytokines, including TNF-α, IFN-γ, and IL-1β, and the induction of neuroendocrine and neurochemical changes, leading to depression." (PMID 31141940, 2019). "Compared with the depression group, the miR-301b inhibitor and SN50 groups demonstrated reduced levels of TNF-α, IL-Iβ and COX-2 (p < 0.05), and opposite trends were observed in the miR-301b mimic group (p < 0.05)." (PMID 30962417, 2019). "Higher levels of interleukin (IL)-1β, IL-6, tumor necrosis factor (TNF)-α, and C-Reactive Protein (CRP) were reported in patients with depression by many investigators." (PMID 31252530, 2019). "It has been previously shown that major depressive disorder (MDD) patients exhibited higher levels of IL-6 and TNF-α in the blood and cerebrospinal fluid (CSF)." (PMID 31068207, 2019). "A meta-analysis found that IL-1β, IL-6, TNF and C-reactive protein (CRP) in peripheral blood are the most reliable biomarkers of inflammation in patients with depression." (PMID 31849598, 2019). "Other findings indicate higher levels of TNFα and IFNγ in in vitro-stimulated CD8+ T cells isolated from patients with depression and IFNγ levels correlate with the severity of the condition." (PMID 31379879, 2019). "A handful of previous studies have shown that increases in circulating inflammatory cytokines, including IL-1, TNF-α, and IFN-γ, have been validated in depression." (PMID 31049023, 2019). "We found that there were significant interactions between the withdrawn/depression items on the CBCL-C and TNF-α, as well as between the thought problems item on the CBCL-C and TNF-α in subjects who had received DM-MPH treatment." (PMID 31333511, 2019). "The repeated-measures analysis of variance (ANOVA) was used to detect the interaction between withdrawn/depression (or thought problems) of CBCL-C and TNF-α." (PMID 31333511, 2019). "A number of studies have indicated that various cytokines, such as IL-1β, IL-2, IL-6, TNF-α, and IFN-γ in serum or plasma of patients with depression were significantly increased." (PMID 31231295, 2019). "In the first mechanism, DHA and EPA can lead to decrease in production of proinflammatory cytokines, such as tumor necrosis factor (TNF)-α42, interleukin (IL)-1β, IL-2, and IL-6, which are determined by eicosanoid discharge and related to depression." (PMID 31383846, 2019). "Significant interactions were found between the withdrawn/depression items on the CBCL-C and TNF-α, as well as thought problems on the CBCL-C and TNF-α in subjects who had received DM+MPH treatment." (PMID 31333511, 2019).
depression (continued). "The excessive exposure to LPS induces TNF-α expression in the brain and suppresses BDNF expression, leading to the occurrence of anxiety/depression." (PMID 30979031, 2019). "Several behavior tests (sucrose preference test (SPT), forced swimming test (FST) and tail suspension test (TST)) and biochemical parameters (IL-6, TNF-α and SOD levels) were used to evaluate the antidepressive effect of PF on LPS-induced depression model." (PMID 31052597, 2019). "Moreover, the observed increases in both IFN-γ: IL-4 and TNF-α: IL-4 ratios in the SA and SA + SD groups suggest that an inflammatory process takes place in vulnerable subjects with severe anxiety, becoming conspicuous as depression emerges in women displaying severe depression." (PMID 30943938, 2019). "Inflammation is triggered by the release of inflammatory cytokines such as interleukin (IL)-1β IL-2, IL-6, tumor necrosis factor alpha (TNF-α), and C-reactive protein (CRP), which all have been found to be up-regulated in patients with depression." (PMID 31212946, 2019). "Several behavioral tests (SPT, BW, FST and TST) and biochemical parameters (IL-6, TNF-α and SOD) were used to evaluate the antidepressive effects of PF on an LPS-induced depression model for the first time." (PMID 31052597, 2019). "Proinflammatory cytokines like IL-1β, IL-6, TNF-α and IFN-γ are markers involved in the pathophysiology of depression." (PMID 29569964, 2018). "In contrast, we observed significantly decreased levels of pro-inflammatory cytokines IL-1α, TNF-α and chemokine MIP-3α in Abuse+Depression groups compared to Controls." (PMID 29894487, 2018). "Although many markers for depression had been identified previously, such as CRP, tumor necrosis factor-α (TNF-α), IL-6, the brain-derived neurotrophic factor (BDNF), and so on, the predictability of a single marker was poor." (PMID 30095631, 2018). "Baseline depression, measured by SF-36 mental health scale and DAS28, independently predict flare events in patients with sustained LDA who taper their anti-TNF agents." (PMID 29862047, 2018). "Increased levels of pro-inflammatory interleukin (IL)-1β, IL-6, and tumor necrosis factor (TNF)-α and decreased levels of anti-inflammatory IL-1 receptor antagonist and IL-10 are the most commonly reported cytokines in the depression literature." (PMID 29559928, 2018). "This supports important recent findings that anti-TNFα treatment can mitigate depressive symptoms in IBD and additionally improve cognitive deficits in major depressive disorder." (PMID 29518097, 2018). "The pairwise comparisons of IL-6, TNF-α and CRP in patients with different depression degrees in observation group showed statistically significant differences (P<0.05)." (PMID 30181997, 2018). "Increased mRNA levels of TNF-α and TNF-RII in lymphocytes were found for depression patients, and increased levels of serum TNF-RII in heart failure and depression patients." (PMID 29799484, 2018). "Other studies have not found any correlations between L-6, IL-8, IL-10, TNF-α, FIQ and depression, IL-6 and depression or anxiety, IL-6 and pain score, FIQ, or TNF-α." (PMID 29849487, 2018). "Convergent evidence of higher peripheral IL-1β, IL-6, TNF-α and CRP levels would support the psychoneuroimmunology theory as contributory to depressive syndromes and Alzheimer’s disease in elderly." (PMID 30104698, 2018). "Increased mean plasma levels of pro-inflammatory cytokines such as the tumor necrosis factor alpha (TNF-α), interleukin-1 (IL-1) and interleukin-6 (IL-6) have been reported in patients with clinical depression." (PMID 28415673, 2017). "Patients with major depression also often show increased inflammatory markers, including C-reactive protein (CRP), interleukin-6 (IL-6), and tumor necrosis factor (TNF)-α, relative to controls." (PMID 28670290, 2017).
depression (continued). "Another study conducted in Europe recruited a psychiatric patient population, which had shown high levels of TNF-α and soluble TNF-receptors (p55 and p75) in past history patients or those currently facing depression." (PMID 27187381, 2016). "We confirmed that the M1 markers (IL-1β, IL-6, TNFα, iNOS, and CCL2) were induced and that the M2 molecules (Ym1, Arg1, IL-4, IL-10, and TGFβ) were impaired in depression." (PMID 27716270, 2016). "Recent research has begun to reveal that the pro-inflammatory cytokines, particularly, tumor necrosis factor-α (TNF-α), play an integral role in the pathophysiology of depressive disorders and the mechanism of antidepressant treatment." (PMID 27187381, 2016). "Proinflammatory cytokines, particularly IFN-γ and TNF-α, activate IDO and lead to the conversion of tryptophan to kynurenine which in rodents elicits depression-like behavior." (PMID 25218901, 2015). "CRP, TNF-α, and e-Sel were found to have significant moderating effects on the development of storage LUTS (1.06, 0.91–1.96, R2 change: 12.7%), depression (1.17, 1.01–1.54, R2 change: 9.8%), and anxiety (1.35, 1.03–1.76, R2 change: 10.6%), respectively." (PMID 26445118, 2015). "In addition, based on the fact that cytokines could have large influence on the HPA axis, evidence on the increase of cytokines such as interleukin 1 (IL-1), interleukin 6 (IL-6) and tumor necrosis factor alpha (TNF-α) among the patients with depression and anxiety may further support this theory." (PMID 26222511, 2015). "Interestingly, it has been determined that pro-inflammatory molecules, such as IL-1β and TNFα, induce depression-like symptoms, and reduction of their circulating levels could diminish depressive symptoms, suggesting linkage between inflammation and depression." (PMID 25402828, 2014). "The investigated pro- and anti-inflammatory cytokines TNF, IL-6, IL-8, and IL-10 as well as DOR were expressed in skin from the upper and lower leg of patients with FMS, depression, and healthy controls." (PMID 25240423, 2014). "Our results indicated that 6 weeks of CUMS exposure induced significant depression-like behavior, with low 5-HT and NE levels, high TNF-α and IL-6 in brain and high hippocampal TNF-α, IL-6, P-NF-κBP65, and 5-HT2AR levels, and low BDNF expression levels." (PMID 25587342, 2014). "Depression has been characterised as an increased inflammatory status (inflammaging) including elevated levels of pro-inflammatory cytokines, including IL6, TNFα and IL1β." (PMID 25628751, 2014). "Moreover, some studies indicated that depression and psychological stress may induce an immune function imbalance and stimulate the production of proinflammatory cytokines, such as interleukin (IL)-1, IL-6 and tumor necrosis factor (TNF)." (PMID 25551389, 2014). "Depression and anxiety were analyzed using the Hospital Anxiety and Depression Scale (HADS), and serum levels of IL-1β, IL-6, IL-8, IL-10, IL-12, TNF-α, and TGF-β were measured by Cytometric Bead Array." (PMID 25309921, 2014). "Several studies reported increased levels of proinflammatory cytokines, for example, tumor necrosis factor-alpha (TNF-α) and interleukin-6 (IL-6) in depressive disorders." (PMID 25587342, 2014). "Experimental and clinical evidence has suggested that depression and depressive symptoms are accompanied by elevated levels of pro-inflammatory cytokines, including IL6, TNFα and IL1β." (PMID 23876747, 2013). "This study demonstrated that depressed patients with higher levels of the inflammatory markers TNF-α and CRP showed a decrease in depression rating scores over the course of the study." (PMID 24385966, 2013). "Furthermore, increased production of IL-6, IL-1β, IFN-γ and TNF-α, as well as signs of an acute phase response, i.e. increased production of positive acute phase proteins (APPs) and decreased production of negative APPs, are associated with depression." (PMID 23544139, 2013).
depression (continued). "For example, a recent meta-analysis found a significant correlation between tumor necrosis factor (TNF-α), IL-6, and CRP with depression in humans." (PMID 23382717, 2013). "Anti-TNF-α increased IBDQ scores and reduced all depression scores; however only SCL-90 depression scores remained decreased after correction for HBI." (PMID 23544139, 2013). "The plasma levels of TNF-α and soluble TNF receptors are increased in patients with major depressive disorders treated with mirtazapine." (PMID 22808019, 2012). "The main results were similar, with the exception that TNF-α and UPDRS motor scores also became significant in the second model with HAD depression as dependent variable (β = 0.31, p<.005; β = 0.28, p<.009)." (PMID 23082161, 2012). "In fact, numerous studies have indicated major depression as an inflammatory state with elevated levels of proinflammatory cytokines, e.g. Interleukin IL-6, IL-12, interferon (IFN)-γ, IL-1 and tumor necrosis factor (TNF)-α." (PMID 23046564, 2012). "In the patient group, absolute values of TNF-α correlated significantly with FACIT scores (Spearman’s Rho = −0.19, p = .05), HAD depression scores (Spearman’s Rho = 0.35, p = .001) as well as the HAD anxiety scores (Spearman’s Rho = 0.21, p = .03)." (PMID 23082161, 2012). "For example, two recent meta-analyses concluded that increased plasma levels of TNF-α, IL-6, IL-1, and CRP accompany major depression." (PMID 22738397, 2012). "For example, upregulation of interleukin-1 (IL-1α and β) and tumor necrosis factor (TNF)-α, both components of the chronic inflammatory response, occurs with onset of depression and headache; both are frequently described as late clinical sequelae of TBI." (PMID 22606066, 2012). "Given evidence of genetic interaction between TNF and MTHFR, as well as gene-by-environment interaction in comorbid depression with AUD, we next sought to understand TNF and MTHFR in a cellular context." (PMID 18822146, 2008). "Our results suggest that the proinflammatory cytokines (IL-2, IL-12, and TNF-α) and MCP-1 were significantly higher, whereas anti-inflammatory cytokines IL-4 and TGF-β1 were significantly lower in patients with major depression than those of healthy controls." (PMID 18317531, 2007). "In this study, we aimed to explore the role of IL-2, IL-4, IL-12, TNF-α, TGF-β1, and MCP-1 in major depression and to investigate the effects of sertraline therapy." (PMID 18317531, 2007). "The mean levels of HDRS (P < .001), IL-2 (P < .001), IL-12 (P <.001), TNF-α (P < .001), and MCP-1(P < .001) were significantlyhigher in patients with major depression than in controls." (PMID 18317531, 2007). "A bibliometric analysis conducted between 2004 and 2023 on neuroinflammation in depression highlighted the NLRP3 inflammasome, microglia, tumor necrosis factor‐alpha (TNF‐α), and brain‐derived neurotrophic factor (BDNF) as central components in the underlying pathogenic mechanisms." (PMID 41479745, 2026). "Meta-analyses and systematic reviews corroborate these findings, showing increased levels of interleukin-6 (IL-6), interleukin-8 (IL-8), tumor necrosis factor-alpha (TNF-α), and C-reactive protein (CRP) across major psychiatric disorders, including depression, anxiety, schizophrenia, and BD." (PMID 41598300, 2026). "TNF-α, IL - 1β, IL - 6, and IL - 17 each demonstrated significant positive correlations with HADS-A scores (P < 0.05), the prevalence of anxiety (P < 0.05), HADS-D scores (P < 0.05), and the incidence of depression (P < 0.05 for all)." (PMID 41000397, 2025). "Encouragingly, research has identified that TNF-α, IL-1, and IL-6 mediate CRF development, indicating that CRF may share some neurophysiological mechanisms with mental health disorders like depression." (PMID 39935799, 2025).